NLRP3 (NLR family pyrin domain containing 3)
Diseases named in the same sentence as NLRP3 in open-access papers (continued):
Sharing a sentence is not in itself a finding about the gene and the disease.
cardiovascular diseases (continued). "The role of NLRP3 inflammasome signaling pathways and the SGLT-2 cotransporter in inflammatory and oxidative stress-induced processes related to various cardiovascular diseases is becoming increasingly clear and compelling." (PMID 39594530, 2024). "Our findings reveal that both HIV and nicotine amplify NLRP3 inflammasome activity, oxidative stress, and mitochondrial dysfunction, which may contribute to chronic inflammation, viral persistence, and worsening of comorbid conditions such as cardiovascular disease in PWH." (PMID 39599911, 2024). "The findings suggest a link between IFI16, NLRP3, and HIV progression, emphasizing their potential role in comorbidities such as cardiovascular disease." (PMID 39000248, 2024). "In cardiovascular disease, TMAO has been indicated to activate the NLRP3 inflammasome through ROS induction." (PMID 36895266, 2023). "Taken together, our studies strengthen the view that geniposide administration inhibits the pyroptosis mediated by NLRP3 inflammasome via the AMPK pathway to mitigate MI/RI, thus putting forward a new treatment strategy for cardiovascular diseases." (PMID 35715805, 2022). "In recent years, the NLRP3 inflammasome complex has been recognized as playing a critical role in cardiovascular diseases, but not in neonatal RVPO models." (PMID 40394014, 2025). "BHB acts as an endogenous NLRP3 inflammasome inhibitor, reducing inflammatory responses, and increasing circulating BHB levels may treat NLRP3 inflammasome-related cardiovascular diseases." (PMID 40806491, 2025). "However, our findings further support the involvement of IFI16 and NLRP3 inflammasomes in HIV pathogenesis involving increased release of both IL-1 isotypes that may clearly also be related to the increased occurrence of certain comorbidities such as cardiovascular disorders in PWH." (PMID 39000248, 2024). "ROS and NLRP3 inflammasome, as important regulators of pyroptosis, have shown the potential to prevent and treat cardiovascular diseases, but their specific mechanisms have not been fully elucidated." (PMID 36873396, 2023). "We show that an inhibitor of NLRP3 will also reduce the toxic effects of NETs and propose that PAD inhibitors may improve inflammasome-driven human disorders, including cardiovascular disease and thrombosis." (PMID 34122445, 2021). "H2O2-induced HUVEC senescence was alleviated by Gen via suppressing the TXNIP/NLRP3 axis, which may offer a potential therapeutic approach for improving HUVEC senescence and provide a new direction for the treatment of cardiovascular disease." (PMID 34663173, 2021). "Thus, lipoproteins possess major anti‐inflammatory functions that hinder the NLRP3 inflammasome‐activating signals, particularly those exerted by SAA, which has important implications in the pathogenesis of cardiovascular diseases." (PMID 34377468, 2021). "Although the molecular mechanism leading to the development of RT-induced cardiovascular diseases is still unknown, the scientific community has focused on the NOD-like receptor family pyrin domain-containing 3 (NLRP3) inflammasome as a potential key player in the onset of this category of diseases." (PMID 41272654, 2025). "The NLRP3 inflammasome and GSDMD pathways play pivotal roles in the regulation of inflammatory responses and pyroptosis, making them attractive targets for therapeutic intervention in a wide range of diseases, including autoimmune disorders, neurodegenerative diseases, and cardiovascular diseases." (PMID 40832584, 2025). "However, there is a lack of established clinical drugs specifically targeting NLRP3 inflammasome to manage cardiovascular diseases." (PMID 38317229, 2024). "Recent studies have shown that NLRP3 inflammasomes recognize nonmicrobial danger signals and induce the release of the proinflammatory cytokine interleukin- (IL-) 1β, leading to sterile inflammation in cardiovascular disease." (PMID 33628380, 2021).
cardiovascular diseases (continued). "NLRP3 inflammasomes recognize non-microbial danger signals and induce release of proinflammatory cytokine interleukin (IL)-1β, leading to sterile inflammation in cardiovascular disease." (PMID 27225830, 2016).
inflammation (225 papers, 2011 to 2026). Aberrant reaction of the microcirculation characterized by movement of fluid and leukocytes from the blood into extravascular tissues. "In IBD, this protein is associated with activation of the NLRP3 inflammasome, contributing to chronic intestinal inflammation." (PMID 41090750, 2025). "Abnormal activation of NOD-like receptor family pyrin domain-containing 3 (NLRP3) inflammasome is an important cause of intestinal inflammation." (PMID 39334766, 2024). "Elevated IL-1β and IL-18 production by NLRP3 inflammasome-mediated pyroptosis of human primary trophoblasts has been implicated in the induction of placental inflammation and PE syndrome." (PMID 36829486, 2023). "VDR has anti-inflammatory effects, and the VDR/NLRP3 (nucleotide-binding oligomerization domain-like receptor family pyrin domain containing 3) pathway has been suggested to be linked to pancreatic inflammation." (PMID 37808100, 2023). "Excessive activation of the NLRP3 inflammasome is mechanistically linked to diverse pathophysiological conditions, including airway inflammation." (PMID 35408502, 2022). "In summary, the bacteria and viruses that cause CAP can also induce pyroptosis through the NLRP3 inflammasome pathway, which is crucial to the damage of airway cells and the formation of acute lung inflammation." (PMID 36248872, 2022). "Recent studies have shown that PM2.5-induced pulmonary inflammation is associated with activation of NOD-like receptor protein 3 (NLRP3) and caspase-1 pathway, which can trigger cell pyroptosis." (PMID 34147136, 2021). "NLRP3 inflammasome-dependent, IL-1β-mediated IL-17 responses have been associated with neutrophilic airway inflammation and AHR." (PMID 32423405, 2020). "The NOD-like receptor family, pyrin domain containing-3 (NLRP3) inflammasome has been implicated in renal inflammation and fibrosis." (PMID 30483252, 2018). "Given the regulation of inflammation of NLRP3, we aimed to evaluate its role in liver inflammation in mice after BU/CY + HSCT and showed NLRP3 inflammasome was associated with liver inflammation and subsequent liver damage." (PMID 26635145, 2015). "More importantly, we have demonstrated in animal experiments that the protective effect of IAld on intestinal inflammation is associated with the NLRP3 inflammasome, as IAld treatment significantly reduced the LPS-induced expression level of the caspase-1 protein, an NLRP3 inflammasome effector." (PMID 39334766, 2024). "Research has demonstrated that NLRP3 inflammasome activation in mouse AMs is associated with mechanical ventilation-induced lung inflammation and injury and with lung pathology in response to exposure to multiwalled carbon nanotube (MWCNT) nickel contamination, which is consistent with our results." (PMID 39420831, 2024). "Furthermore, we investigated the molecular mechanism underlying the aggravation of gut inflammation by Ybt and found that NLRP3-pathway-induced pyroptosis is closely related to the gut inflammation caused by E. coli-Ybt." (PMID 37511208, 2023). "However, lower levels of pro-inflammatory cytokines in the colon tissues of the NLRP3-deficient mice suggested that decreased NLRP3 inflammasome activation is required for amelioration of acute and chronic intestinal inflammation." (PMID 37191444, 2023). "Therefore, inhibition of the TLR4/NLRP3 signaling pathway is an effective therapy for the treatment of inflammation-linked diseases, such as IVDD." (PMID 35506157, 2022). "The NLRP3 inflammasome dysfunction has been implicated in a variety of inflammation diseases." (PMID 36299604, 2022). "Our findings may provide novel insight into the detailed mechanisms underlying the NLRP3 inflammasome and IL-1β synthesis observed in severe neutrophilic asthmatic airway inflammation." (PMID 34064821, 2021). "We first examined whether the stimulation of the NLRP3 inflammasome is associated with HDM/LPS-induced neutrophilic airway inflammation." (PMID 34064821, 2021).
inflammation (continued). "Scientific evidence has demonstrated that NLRP3 over-activation during bowel inflammation could be associated with a breakdown of enteric immune balance, suggesting the involvement of NLRP3 in the pathogenesis of various immune-mediated diseases as IBS." (PMID 33233503, 2020). "To test this hypothesis, we used mice deficient in inflammasome-related molecules such as NLRP3, Casp1, and IL-1β, and found that the cardiac glycoside ouabain induces cardiac inflammation and dysfunction via NLRP3 inflammasomes when mice were primed with lipopolysaccharide (LPS)." (PMID 28493895, 2017). "ASI ameliorated indomethacin‐induced intestinal inflammation in rats by inhibiting the activation of NLRP3 inflammasome and reducing the release of IL‐1β and IL‐18." (PMID 40586619, 2025). "As noted, blocking the NLRP3 inflammasome with IL-33 or specific inhibitors reduced brain inflammation and significantly improved outcomes in mice." (PMID 41002937, 2025). "Our in vivo experiments confirm that NLRP3 inflammasomes exacerbate endothelial inflammation and apoptosis through the caspase-1 pathway." (PMID 41323268, 2025). "It attenuates cardiac inflammation and enhances cardiac function by reducing NLRP3 inflammasome activation and pyroptosis, thereby exerting cardioprotective effects." (PMID 39925805, 2025). "In conclusion, this study shows that NLRP3 activation in neutrophils induces brain inflammation through neutrophil infiltration and BBB disruption via CXCL1/2 secretion and subsequent activation of the CXCL1/2-CXCR2 signaling axis." (PMID 40413505, 2025). "The reduction of NLRP3-mediated synovial inflammation by UC-MSCs is an important therapeutic direction for UC-MSCs in the treatment of OA." (PMID 40919498, 2025). "Our therapeutic strategy focuses on the NLRP3 inflammasome, a critical mediator of both acute and chronic liver inflammation, primarily acting through macrophages." (PMID 40521185, 2025). "Among these, NOD-like receptors (NLRs), including NOD1, NLRP1, and NLRP3, serve as vital interfaces between microbiota and systemic chronic inflammation." (PMID 38336763, 2024). "In our present study, TA had a beneficial effect on renal inflammation in DN mice by reducing the release of pro-inflammatory cytokines, along with suppressing the NLRP3/ASC/Caspase-1 signaling pathway, and further reduces renal interstitial fibrosis." (PMID 39193336, 2024). "The efficacy of Trig in attenuating bleomycin-induced pulmonary inflammation and fibrosis through modulation of the NLRP3 inflammasome and Hippo signaling pathway had been reported." (PMID 38877465, 2024). "In the present study, lipopolysaccharide (LPS)-induced intestinal inflammation models (in vivo and in vitro) were used to explore the molecular mechanism of microbial-derived IAld in the regulation of NLRP3 inflammasome activation and gut barrier function." (PMID 39334766, 2024). "Our laboratory has extensively investigated the critical role of the NLRP3 inflammasome in mediating urothelial inflammation." (PMID 38682210, 2024). "Extensive research has established that the activation n of the NLRP3 inflammasome contributes significantly to renal inflammation, leading to renal impairment." (PMID 39104818, 2024). "Mdivi-1, an inhibitor of DRP1, was recently found to alleviate inflammation-related diseases by inhibiting NLRP3 inflammasome." (PMID 37386574, 2023). "NLRP3 inflammasomes are critical in ISO-induced cardiac inflammation as they promote the cleavage and activation of IL-18, resulting in the initiation of cardiac inflammation." (PMID 37298222, 2023). "One study showed that the activation of NLRP3 inflammasome played an important role in DSS-induced colonic inflammation damage." (PMID 37685978, 2023). "Many lines of evidence suggest that RSV can activate the NLRP3 inflammasome and induce inflammasome-related airway inflammation, even pyroptosis, similar to other RNA viruses." (PMID 37798799, 2023).
inflammation (continued). "On the other hand, another study found that MCC950's suppression of the NLRP3 inflammasome led to severe renal inflammation and injury in a model of diabetic kidney mice." (PMID 38114914, 2023). "Our results show an upregulation of NLRP3 in the well-established in vitro model for chronic muscle inflammation, as used for IBM upon stimulation with IL-1β and IFN-γ for 24 h, 48 h, and 72 h, creating a proinflammatory milieu." (PMID 37445853, 2023). "Ang II-induced cardiac inflammation, fibrosis and hypertrophy were shown to be prevented by blocking NLRP3 inflammasome activation in macrophages and cardiomyocytes." (PMID 36978920, 2023). "Animal models of lipopolysaccharide-induced amniotic inflammation showed increased mRNA expression of inflammatory-related genes (NLRP3, Caspase-1, IL-1β), and higher concentrations of NLRP3 protein in fetal membranes and deciduae than before preterm delivery." (PMID 37571360, 2023). "In the setting of diet-induced liver inflammation and fibrosis, levels of inflammasome components, including NLRP3, pro-IL-18, pro-IL-1β, ASC, and caspase-1 were found to be elevated in both MASH patients and experimental MASH animal models." (PMID 37664463, 2023). "This is similar to LPS in liver inflammation, which is related to the activation of inflammasome nod-like receptor protein 3 (NLRP3) and the production of interleukin (IL)-1β through activation of the nuclear factor-κB (NF-κB) pathway." (PMID 37744692, 2023). "Because of the important role of the NLRP3-inflammasome in the onset and maintenance of cardiovascular inflammation, we assessed the extend to which inflammasome-activation is influenced in atherosclerotic plaques in P2X4-deficient mice." (PMID 35181718, 2022). "We previously reported the mediating roles of BLT2 in regulating the production of IL-17 and NLRP3-dependent IL-1β in neutrophilic airway inflammation." (PMID 36428547, 2022). "Our previous studies have shown that NLRP3 inflammasome and autophagy play an important role in liver inflammation." (PMID 35743108, 2022). "Our results suggested that the NLRP3 inflammasome-mediated pyroptosis participated in synovial inflammation of TMJOA." (PMID 36466156, 2022). "Blocking pyroptosis of macrophages by inhibiting the NLRP3 inflammasome or caspase-1 reduces silica-mediated pulmonary inflammation and fibrosis." (PMID 35819638, 2022). "Increased NLRP3 is, of course, associated with various inflammatory lung pathologies and aberrant activation of NLRP3 inflammasome contributes to ARDS induced lung inflammation and injury." (PMID 35144622, 2022). "Pirfenidone ameliorates lipopolysaccharide-induced pulmonary inflammation and fibrosis by blocking NLRP3 inflammasome activation and reducing lung injury induced by COVID-19 pneumonia; it also reduces plasmatic and pulmonary IL-6 concentration." (PMID 36010377, 2022). "It is reported that a selective inhibitor of the p38 MAPK signaling pathway, SB203580, suppresses the NLRP3/caspase-1-dependent pyroptosis in AMs, which results in the amelioration of lung inflammation." (PMID 35819638, 2022). "Selective inhibition of NLRP3 inflammasome effectively prevents airway allergic inflammation and AHR." (PMID 35819638, 2022). "Liquiritigenin (Rt: 3.034), is reported to ameliorate renal inflammation through suppression of AQP4/NF-kB/IkBa signaling as well as NLRP3 inflammasome in hyperuricemic rats, thus showing anthyperuricemic effects." (PMID 36474572, 2022). "DM-induced cardiac inflammation is driven by NLRP3 inflammasome, which can be activated by reactive oxygen species (ROS)." (PMID 35057549, 2022). "Increasing evidence has demonstrated that activation of the NLRP3-NF-κB signalling pathway and subsequent release of inflammatory cytokines are major factors in renal inflammation induced by CaOx nephrocalcinosis." (PMID 36408256, 2022).
inflammation (continued). "Expression of miR-223 in neutrophils inhibits the NLRP3/IL-1β axis, reduces airway inflammation, and reduces NLRP3 (Nucleotide-binding oligomerization domain, leucine-rich repeat and pyrin domain-containing 3) levels and IL-1β release." (PMID 35634335, 2022). "To investigate the role of the NLRP3/caspase-1 pathway in a model of acute intestinal inflammation, we modified a previously established in vitro triple culture model of the healthy and inflamed intestine (Caco-2/HT29-MTX-E12/THP-1)." (PMID 35911682, 2022). "18β-Glycyrrhetinic acid (18β-GA) inhibited the activation of NLRP3 inflammasome and NLRP3-related pyroptosis, decreased ROS level and pulmonary inflammation, improved alveolar development of BPD rats." (PMID 36685920, 2022). "This is consistent with a recently published article that showed metformin abrogated macrophage NLRP3 inflammasome activation and pulmonary inflammation." (PMID 35910360, 2022). "In the present study, we observed high expression of mitochondrial ROS and TXNIP in cardiac tissue, which triggered NLRP3 overexpression and cardiac inflammation." (PMID 34257682, 2021). "Caspase‐1 NLRP3 and ASC are components of NLRP3 inflammasomes that can cause cardiac inflammation and cardiac dysfunction via IL‐1β and TGF‐β1 release." (PMID 33270361, 2021). "In our research, we found that the NLRP3 inflammasome plays a critical role in sympathetic stress-induced cardiac inflammation and cardiac injury." (PMID 34776995, 2021). "Together, our results suggest that the 5-/12-LOX-BLT1/2-linked cascade are necessary for the simulation of the NLRP3 inflammasome and IL-1β synthesis, thus contributing to HDM/LPS-induced neutrophil-dominant airway inflammation." (PMID 34064821, 2021). "Collectively, the inactivation of the NLRP3/caspase‐1 pathway by MCC950 alleviated lung inflammation induced by PM2.5 exposure in mice model." (PMID 32996690, 2021). "Our results highlight the importance of myeloid Foxo1 signaling as a key regulator of the NEK7/NLRP3 activation and hepatocyte necroptosis in IR stress-mediated liver inflammation." (PMID 33288903, 2021). "In most of the studies, cardiac inflammation was shown to induce fibrosis following activation of the NLRP3 inflammasome." (PMID 34776995, 2021). "We have shown that hepatic IR activates liver macrophages and induces toll-like receptor 4 (TLR4) or NLRP3 activation, which drives the innate immunity-mediated liver inflammation." (PMID 33288903, 2021). "Supporting this pathomechanism, inhibition of the PAMP responsive NLRP3 inflammasome by the small molecule MCC950 reduced the severity of liver inflammation and fibrosis in NASH models." (PMID 34298870, 2021). "The NLRP3 inflammasome has been known to play a role in many inflammatory diseases, and its excessive activation induces intestinal and breast inflammation and tissue damage." (PMID 34594329, 2021). "NLRP3, overactivated in global and myeloid cell-specific conditional mutant NLRP3 knock-in mice, leads to serious liver inflammation and fibrosis." (PMID 32093389, 2020). "As an endogenous cytoprotective enzyme, HO-1 was proved has the ability to suppress the NLRP3 signaling pathway and then inhibit LPS/D-Gal-induced hepatic inflammation in mice." (PMID 33536915, 2020). "In conclusion, our results demonstrated that H2S ameliorated PM-conducted lung emphysema and airways inflammation by scavenging ROS generation, inhibiting NLRP3 inflammasome formation, and anti-apoptosis via Nrf2 manner." (PMID 32116706, 2020). "In Xu's study, they reported that statin use enhanced bleomycin‐induced lung inflammation and fibrosis through a mechanism involving increased mtROS generation to enhance NLRP3‐inflammasome activation." (PMID 32977368, 2020).